MTOR (mechanistic target of rapamycin kinase)
Diseases named in the same sentence as MTOR in open-access papers (continued):
Sharing a sentence is not in itself a finding about the gene and the disease.
endometrial cancer (continued). "Endometrial cancer organoids were amenable to drug screening of standard chemotherapies, demonstrating patient-specific drug responses, in particular sensitivity to mTOR inhibition in line with mutations in the PI3K/AKT/mTOR signalling pathway." (PMID 34283069, 2021). "Around 80% of endometrial cancers are endometrioid tumours caused by overstimulation of the PI3K-Akt-mTOR and MAPK/ERK1/2 signalling pathways by unopposed oestrogen." (PMID 34771605, 2021). "Noticeably, co-treatment of FGFR2 and mTOR has a synergistic effect on the growth of endometrial cancer cell lines bearing an activating FGFR2 mutation, irrespective of PTEN status." (PMID 33193890, 2020). "In endometrial cancer cells, metformin induced G1 arrest and caused apoptosis by suppressing mTOR signaling." (PMID 28252027, 2017). "Considering the high level of PTEN mutations in endometrial cancer, many trials tested mTOR inhibitors in this tissue." (PMID 28008141, 2017). "Significant genetic alterations in the PI3K-mTOR pathway are observed in human endometrial cancer and the loss of Pten or overactivation of mTOR signaling results in the development of similar tumours in mouse models." (PMID 27980219, 2017). "Taken together, the four diseases (LAM, TSC, SLE, and endometrial cancer) appear to share a robust association with mTOR pathway activation." (PMID 27377753, 2016). "Recently, the mTOR pathway has been found to play a crucial role in the development of endometrial cancer with high frequency of mutations in PTEN and/or PIK3CA; knowledge about genetic alterations involved in this pathway offer potential treatment strategies." (PMID 27377753, 2016). "No previous publication has reported on its association with both SLE and endometrial cancer, and this unique case suggests a possible common etiology involving dysfunction of cell regulation functions of the mTOR pathway." (PMID 27377753, 2016). "A number of studies have suggested that the mTOR signaling pathway is important in tamoxifen-associated endometrial cancer." (PMID 25788989, 2015). "Previous studies indicate that PTEN inactivation, PIK3CA mutation, and mTOR dysregulation are common molecular signatures for endometrial carcinoma." (PMID 22039466, 2011). "Therefore, LAM, TSC, and endometrial cancer appear to share an association with mTOR pathway activation, explaining why they can occur in the same patient." (PMID 39156285, 2024). "Endometrioid endometrial cancers are known to harbor mutations in PI3K/AKT/mTOR pathway genes." (PMID 37853941, 2024). "Importantly, we demonstrated for the first time that the nuclear localization of mTOR was positively associated with higher-grade endometrial cancer and FIGO stages IB–IV." (PMID 37176048, 2023). "To conclude, our findings suggest that WNT-1 levels in the membrane may be used to rule out high-risk neoplasms, whereas cytoplasmic WNT-1 and nuclear mTOR may be used for confirmation of high-risk endometrial cancer." (PMID 37176048, 2023). "Our current research suggested that the WNT-1 and mTOR pathways may be potential biomarkers of high-risk endometrial cancer." (PMID 37176048, 2023). "MTOR mutations have been detected in endometrial cancer and they may be regarded as primary drivers of carcinogenesis." (PMID 37176048, 2023). "PTEN mutations play a key role in the pathogenesis of type I endometrial cancer, while mutations found in mTOR may be mainly involved in the pathogenesis of type II endometrial cancer." (PMID 37644107, 2023).
endometrial cancer (continued). "Overall, these RiBi factors might correspond to the first RiBi‐associated predictive markers of aromatase and mTOR inhibitor combination therapy at least in advanced stages of endometrial cancer." (PMID 36370117, 2023). "Additionally, estrogen activates mTOR signaling, a pathway implicated in endometrial cancer development and progression." (PMID 35409166, 2022). "Triptolide could induce cell cycle arrest in G2/M phase of human endometrial cancer cell line Ishikawa, which was closely associated with the down-regulation of Akt and mTOR protein phosphorylation and mRNA in PI3K-Akt-mTOR pathway." (PMID 35646647, 2022). "However, PARPis also hyperactivate the MAPK and PI3K/AKT/mTOR pathways in PTEN-deficient endometrial carcinoma (EC), which allows the emergence of PARPi resistance." (PMID 35725817, 2022). "The mTOR missense mutations are found in a wide variety of malignancies, most notably in roughly 7.5% of lung adenocarcinomas, 6% of clear cell renal cell carcinomas, 5% of endometrial carcinomas, and 4% of colorectal carcinomas." (PMID 35402264, 2022). "These mutations lead to high activation of the PI3K/Akt/mTOR pathway in endometrial cancer." (PMID 34831139, 2021). "The central role of PI3K activation in tumor cell biology has prompted an effort to target PI3K and/or downstream kinases such as AKT and mammalian target of rapamycin (mTOR) in endometrial cancers where mutations in PIK3CA have been reported at high frequency in both Type I and Type II tumors." (PMID 31934607, 2020). "Thus, the existence of PTEN mutations might be a predictive biomarker for the PI3K/mTOR inhibitors in endometrial carcinomas." (PMID 22662154, 2012). "Given the role of PTEN in negatively regulating the PI3K/AKT/mTOR pathway, inhibitors targeting this pathway have shown promise in preclinical studies and early-phase clinical trials for endometrial cancer." (PMID 40072110, 2025). "Analysis of PI3K/AKT/mTOR pathway signalling revealed that taxane-resistant endometrial cancer cells had increased pathway activity: taxane-resistant AN3CA cells displayed 6-fold higher phosphorylated-S6 and 3-fold elevation in phosphorylated-AKT." (PMID 40360883, 2025). "In clinical trials, mTOR inhibitors have been combined with endocrine therapy to enhance their efficacy for the treatment of endometrial cancer, yielding favourable outcomes." (PMID 39819881, 2025). "In similarity to clinically approved SNIs (i.e. alpelisib, everolimus and capivasertib) inavolisib, RLY-2608 and STX-478 showed only limited ability to inhibit PI3K/AKT/mTOR pathway signalling in breast and endometrial cancer cells." (PMID 40360883, 2025). "And the axis circ-8073/miR-449a/CEP55 promotes endometrial cancer proliferation via the PI3K/AKT/mTOR pathway." (PMID 41283360, 2025). "In some endometrial cancers, ARID1A loss has been linked to the activation of oncogenic pathways, such as the PI3K/AKT/mTOR signaling pathway." (PMID 40072110, 2025). "Proteomics revealed upregulated proteins linked to commonly dysregulated pathways in endometrial cancer, namely PI3K/AKT/mTOR, MAPK/RAS, and Wnt signaling pathways." (PMID 41284888, 2025). "In endometrial cancer, alterations in the PI3K/AKT/mTOR pathway, often driven by PTEN loss, have established it as a critical therapeutic target." (PMID 41303544, 2025). "Ongoing trials are assessing the combination of immunotherapy and PI3K/AKT/mTOR pathway inhibitors in PTEN-mutant endometrial cancers, including poorly differentiated EC subtypes." (PMID 40072110, 2025). "The mTOR pathway is frequently activated in tumors, and an attractive pathway for novel drug targets in endometrial cancer." (PMID 40227411, 2025). "These pathways include the ECM-receptor interaction, FoxO signaling pathway, pathways in cancer, Hippo signaling pathway, TGF-beta signaling pathway, endometrial in cancer, mTOR signaling pathway, and cell cycle." (PMID 40140178, 2025).
endometrial cancer (continued). "Specifically, five out of six identified miRNAs regulate the FoxO signaling pathway, endometrial cancer, and mTOR signaling pathway." (PMID 40140178, 2025). "In conclusion, our results demonstrate that baicalein, a natural flavonoid, reduces cell viability in endometrial cancer cells by inhibiting the AMPK/PI3K/mTOR pathway and enhances the anti-proliferative effects of metformin." (PMID 41303544, 2025). "mTOR pathway activation reversed the effects of autophagy and cancer hallmarks in endometrial cancer." (PMID 41233892, 2025). "Propofol decreased apoptosis and increased cancer cell viability in cervical and endometrium cancer via blocking HSp70 ribosomal protein S6 kinase pathway, caspase-3, Bax and the mammalian target of rapamycin (mTOR)." (PMID 41233892, 2025). "Current drug therapies for endometrial cancer include platinum-based chemotherapy, progestins, and targeted agents such as mTOR inhibitors and immune checkpoint inhibitors." (PMID 40538398, 2025). "mTOR inhibitors, such as Everolimus and Temsirolimus, directly target the mTORC1 complex and have demonstrated antitumor effects in endometrial cancers by inhibiting cell growth and protein synthesis." (PMID 40072110, 2025). "In this study, we investigated the anti-tumor effects of baicalein in human endometrial cancer, a disease often associated with dysregulation of the PI3K/AKT/mTOR signaling pathway, particularly due to frequent loss of PTEN function." (PMID 41303544, 2025). "Approximately 28.5% of endometrial carcinomas are reported to harbor HR deficiency, accompanied by widespread dysregulation of the PI3K/AKT/mTOR pathway across molecular subtypes." (PMID 41189946, 2025). "Among solid tumors, endometrial carcinoma has the highest rate of alterations in the PI3K/AKT/mTOR pathway, with specific alterations in this pathway observed in 92% of type I and 60% of type II endometrial carcinomas." (PMID 41479912, 2025). "Ridaforolimus’s potential in endometrial cancer treatment, its role in overcoming resistance in certain combinations, and its interaction with the mTOR pathway in specific cancers offer exciting avenues for exploration." (PMID 38584599, 2024). "Similar to mTOR inhibitors, metformin has shown efficacy in clinical trials for endometrial cancer and is considered a promising treatment for endometriosis." (PMID 39579091, 2024). "The effects of metformin on endometrial cancer, endometriosis, and adenomyosis are believed to be mediated through inhibition of the mTOR pathway." (PMID 39579091, 2024). "In endometrial cancer, the presence of activating mutations in fibroblast growth factor receptor 2 (FGFR2) and disruptions in the mTOR pathway have been identified as potential therapeutic targets." (PMID 38584599, 2024). "Isolipurgenin was also reported to inhibit the PI3K/Akt/mTOR signaling pathway and enhance apoptosis in endometrial cancer cells." (PMID 39629212, 2024). "As expected, mTOR activator MHY1485 partially mitigated disulfiram-induced cytotoxicity in endometrial cancer spheroid cells." (PMID 39394200, 2024). "The mutation or deletion of the gene leads to disturbed activation of the PI3K/AKT/mTOR pathway, which occurs in 60%–80% of endometrial cancer cases." (PMID 39188680, 2024). "Our investigation subsequently focused on understanding the influence of mTOR inhibition on endometrial cancer spheroid cell proliferation." (PMID 39394200, 2024). "While clinical trials have demonstrated the efficacy of PI3K/Akt/mTOR inhibitors as monotherapy in endometrial cancer, as of 2024, the European Medicines Agency (EMA) has not granted approval for these inhibitors in endometrial cancer." (PMID 39579091, 2024). "To understand ALDH’s impact on mTOR signaling in endometrial cancer cells, we characterized its functional isoforms." (PMID 39394200, 2024).
endometrial cancer (continued). "mTOR mutations were identified in T cells (MOLT16 T cell leukemia cell line), endometrium cells (HEC59, JHUEM7 endometrial carcinoma cell lines) and kidney cells (SNU349 RCC cell line)." (PMID 39138146, 2024). "Based on the premise that the dysregulation of the PI3K/AKT/mTOR pathway observed in endometrial carcinoma determines hormonal resistance, the combination of mTOR inhibitor with endocrine therapy has been utilized." (PMID 38791945, 2024). "WNT-1 and mTOR levels in the plasma membrane, nucleus, and cytoplasm were evaluated using immunohistochemical staining in a group of 64 patients with endometrial cancer of grades 1–3 and FIGO stages I–IV." (PMID 37176048, 2023). "First, we provided novel insight into WNT-1 and mTOR levels in different cellular compartments in endometrial cancer." (PMID 37176048, 2023). "The primary aim of this study was to assess the levels of the WNT-1 and mTOR proteins in different cellular compartments of endometrial cancer cells." (PMID 37176048, 2023). "PI3K, AKT, and mTOR inhibitors are under investigation in endometrial cancer with promising results in early phase studies." (PMID 37353806, 2023). "The in-vitro experiment confirmed that high-glucose conditions facilitate the development of endometrial cancer via mTOR." (PMID 36927703, 2023). "Our findings demonstrated that oleic acid exhibited anti-tumorigenic activities, dependent on the PTEN/AKT/mTOR signaling pathway, in endometrial cancer." (PMID 38001668, 2023). "In the treatment of endometrial cancer, combined with mTOR inhibitors, KDM1A inhibitors were found to inhibit tumor growth in ex vivo and in vivo experiments." (PMID 36742386, 2023). "Inhibition of the AKT/mTOR pathway by ipatasertib effectively increased the anti-tumor activity of oleic acid in endometrial cancer cells." (PMID 38001668, 2023). "The mTOR pathway promotes endometrial cancer cell proliferation and metabolism and, thus, contributes to tumor initiation and progression." (PMID 37176048, 2023). "This activation of mTOR results in increased growth and proliferation; therefore, the inhibition of mTOR has gained popularity and regulatory approval in the treatment of endometrial cancer." (PMID 36980685, 2023). "The VICTORIA trial thus reveals that targeting the PI3K/AKT/mTOR pathway is of clinical relevance in metastatic endometrial cancer." (PMID 36370117, 2023). "miR-101-3p (miR-101) is downregulated and mTOR and 4EBP1 are upregulated in endometrial cancer cells, promoting proliferation and invasion and suppressing apoptosis, which is reversed by the miR-101-3p mimic and/or si-mTOR." (PMID 36835100, 2023). "This study provides RiBi‐based markers relevant for a better selection of patients with advanced endometrial carcinoma by predicting the response of endocrine therapy combined with mTOR inhibitor." (PMID 36370117, 2023). "Single-agent temsirolimus mTOR inhibition previously demonstrated modest activity in advanced/recurrent endometrial carcinoma, although durable disease stabilization was observed in some patients." (PMID 37839313, 2023). "Other signaling pathways targeted in endometrial cancer include pathways like the mammalian target of rapamycin (mTOR), epidermal growth factor (EGF) and insulin-like growth factor (IGF), where receptors or kinases are targeted by specific inhibitors." (PMID 35328833, 2022). "The inhibition of the PI3K/AKT/mTOR pathway promoted autophagy for the anti-proliferation activity in endometrial cancer cells." (PMID 35860020, 2022). "The mechanisms underlying PKD1 were associated with apoptosis, B cell receptor signaling pathway, endometrial cancer, mTOR signaling pathway, and VEGF signaling pathway." (PMID 35816294, 2022). "Everolimus, an mTOR inhibitor, combined with letrozole, an aromatase inhibitor, is currently used for treatment of recurrent endometrial cancer based upon a positive phase 2 study." (PMID 35887124, 2022).
endometrial cancer (continued). "In a phase II study (MAGGIE), the efficacy of apitolisib (a dual PI3K/mTOR inhibitor) was assessed in patients with advanced endometrial cancer." (PMID 35402264, 2022). "For example, it is shown that LSD1 inhibition is highly synergistic with mTOR inhibitors in endometrial cancer, increasing the limited success that mTOR inhibitors presented." (PMID 35327654, 2022). "FTO-mediated tumorigenic role in endometrial cancer was uncovered and connected to the mTOR pathway, while mTOR’s connection to FTO-obesogenic functions awaits further exploration." (PMID 35409166, 2022). "GSEA results showed that high expression of PKD1 was enriched in apoptosis, and low expression of PKD1 was enriched in B cell receptor signaling pathway, endometrial cancer, mTOR signaling pathway, and VEGF signaling pathway." (PMID 35816294, 2022). "CLDN6 knockdown significantly inhibited endometrial cancer cell proliferation via the PI3K/Akt/mTOR signaling pathway." (PMID 36362009, 2022). "The strategies including letrozole combined with phosphoinositide 3-kinase (PI3K) inhibitors and mammalian target of rapamycin (mTOR) inhibitors, and the potential synergism has already been demonstrated in breast and endometrial cancers." (PMID 36741732, 2022). "The interaction between m6A and the PI3K/AKT/mTor signaling pathway has also been described for endometrial cancer and further entities." (PMID 36050747, 2022). "In line with our study, silencing CCAT2 suppressed endometrial cancer cell growth by inactivation of the mTOR pathway." (PMID 35170195, 2022). "AF suppressed proliferation and promoted apoptosis as well as ferroptosis of endometrial carcinoma cells through the activation of ROS/AMPK/mTOR pathway." (PMID 35635082, 2022). "Apart from endometrial carcinomas, aberrations in mTOR signaling have also been noted in endometrial stromal sarcomas (ESSs)." (PMID 35408777, 2022). "Several studies have shown that downregulation of miR-99b-5p is correlated with the elevated levels of mTOR in PCa and endometrial carcinoma." (PMID 35328346, 2022). "CD47 overexpression activates the PI3K/Akt/mTOR signaling pathway in endometrial carcinoma cell lines to reduce cancer cell apoptosis." (PMID 36016675, 2022). "Metformin has already been described to activate AMPK and decrease mTOR signaling in well-differentiated endometrial cancer cells." (PMID 33946426, 2021). "PRMT6 behaves as an oncogene to promote cell proliferation and migration in endometrial cancer via activation of the AKT/mTOR pathway." (PMID 34522186, 2021). "The major pathways involved in endometrial cancer seem to be PI3K/Akt/mTOR, MAPK, WNT, and FBXW7 signaling." (PMID 33546293, 2021). "miR-199a-3p directly interacts with the 3′-UTR of mTOR and inhibits the mTOR pathway and restrains endometrial cancer cell proliferation as well as increases the sensitivity of HCC cells to doxorubicin-induced apoptosis." (PMID 34869377, 2021). "In line with our results, activation of PI3K/AKT/mTOR signaling pathway promoted epithelial-mesenchymal transition in endometrial cancer." (PMID 34055578, 2021). "Again, CC was able to prevent S6 kinase dephosphorylation and, thus, mTOR inhibition, in all endometrial cancer cell lines." (PMID 33946426, 2021).